IL6 (interleukin 6)
Diseases named in the same sentence as IL6 in open-access papers (continued):
Sharing a sentence is not in itself a finding about the gene and the disease.
tumor (continued). "Its tight binding to IL-6 inhibits IL-6 bioactivity and thus causes apoptosis of tumor cell." (PMID 31552191, 2019). "Studies have shown that the differentiation of macrophages into the M2 phenotype may be caused by prostaglandin E2 (PGE 2) and interleukin 6 (IL-6) produced by tumor cells." (PMID 31850329, 2019). "Alternatively, it is possible that other elements of the tumor microenvironment, such as cancer associated-fibroblasts or other stromal cells, may produce some of the IL-6 and IL-8 observed." (PMID 31781510, 2019). "In addition, Cygb-deficient mice show elevated TNF-α and IL-6 in tumor and non-tumor tissue of the liver and lung." (PMID 31920538, 2019). "Finally, sensing of the tumor-associated cytokines IL-4 and IL-6 by macrophages induced IRE1/XBP1s activity and increases the secretion of proteins that promote cancer cell invasion such as cathepsins." (PMID 31817075, 2019). "Accumulating evidence suggests that M2 macrophages activated by cancer cells could promote activation of STAT3, triggering secretion of several cytokines (IL-6 and IL-10) and this eventually causes increased tumor growth and metastasis." (PMID 30791624, 2019). "Also, compared to WT mice, lower levels of liver markers (AST, ALT, Bil), cytokines (Tnfα, Tgfβ, Il6), and tumor markers (c-Myc, Mmp2, Epcam) in Pecam-1-deficient mice after TAA-application underline the important functions of PECAM-1." (PMID 31344919, 2019). "IL-6 is a pro-inflammatory cytokine that is associated with tumor progression." (PMID 31118047, 2019). "Since MDA-MB-231 and A549 cancer cells lack surface expression of IL-6Rα (unpublished data), it is likely that MH exerts its anti-tumor effect via binding to sIL-6Rα, inhibiting its association with the IL-6 cytokine and ultimately preventing the triggering of the IL-6 trans-signaling pathway." (PMID 31491838, 2019). "Also systemic thermal therapy (STT) induced the activation of IL-6 trans-signaling causing up-regulation of ICAM-1 on tumor vascular endothelium and thus increased the homing of adoptively transferred CD8+ T cells into tumors in mouse models of cancer." (PMID 31231358, 2019). "Myeloid cells chiefly regulate such mechanisms of sIL-6R-mediated immune suppression, along with IL-6-dependent inflammatory processes in the TME have been linked to tumor progression and poor prognosis in several solid cancers, including gastric, breast, colorectal, ovarian, and lung." (PMID 31842362, 2019). "Based on our study, reduced tumor burden was associated with attenuated IL-6 signaling and augmented tumor rejection in the microenvironment, which might mediate the benefit of clinical adoption with aggressive local therapy." (PMID 31315262, 2019). "Tumor-associated macrophages (TAMs) shown to promotes NEPC via IL-6 and STAT3." (PMID 31547070, 2019). "Interestingly, the increase in systemic glucocorticoids in response to IL6-mediated suppression of hepatic ketogenesis was associated with a suppression of anti-tumor immunity." (PMID 31058816, 2019). "In vitro studies have shown that both pancreatic cancer cell lines and CAFs produce IL-6, which might act as an autocrine and paracrine stimulus causing increased tumor cell migration and invasion, as well as epithelial to mesenchymal transition (EMT)." (PMID 30764482, 2019). "Chronic inflammation leads to increased exposure of cholangiocytes to the inflammatory mediators interleukin-6, Tumour Necrosis Factor-ɑ, Cyclo-oxygenase-2 and Wnt, resulting in progressive mutations in tumour suppressor genes, proto-oncogenes and DNA mismatch-repair genes." (PMID 30819129, 2019). "To date, some prognostic markers were investigated in advanced NSCLC, including positron emission tomography parameters, driver gene mutation, number of metastatic sites, interleukin-6, cell-free DNA, circulating tumor cells, inflammation parameters, and tumor-infiltrating lymphocytes (TILs)." (PMID 31623615, 2019).
tumor (continued). "Moreover, inflammatory markers such as IL-6 have also been associated with the malignant transformation of epithelial cells and tumor progression, associating low-grade inflammation with a higher risk of cancer and recurrence in the survival phase." (PMID 31414667, 2019). "However, no study has yet assessed the associations between dietary ORAC and CRC risk underlying the plasma IL-6 level, which is regarded as a tumor-promoting biomarker." (PMID 31795177, 2019). "A subpopulation of α-SMAhigh myofibroblasts were predominantly localized in close proximity with tumor cells, while α-SMAlow cells represented inflammatory CAFs associated with elevated expression of tumor promoting cytokines, including IL-6, and were located more distantly from the tumor cells." (PMID 31068935, 2019). "Altogether, our findings demonstrate that peripheral blood CD45+CD33lowCD11bdim MDSCs suppress CD8+ T cell activity via the IL-6/IL-8-arginase I axis and are positively associated with GC tumor progression and negatively associated with overall patient survival." (PMID 29988030, 2018). "Besides providing a pro-inflammatory status by interaction with DCs, NK and CTL, iNKT have also been found to be able to control tumor growth by killing tumor supportive IL-6-producing CD1d+ CD68+ tumor associated macrophages (TAM)." (PMID 30298063, 2018). "In murine models, inactivation of the tumor suppressor gene STK11/LKB1 led to significant increases in tumor-promoting cytokines and neutrophil activity; treatment of mice with an IL-6 antibody decreased the degree of tumor-associated neutrophils and improved survival as compared to control mice." (PMID 29619344, 2018). "CXCL1 and GM-CSF have been reported to recruit myeloid-derived suppressor cells (MDSCs), a cell type connected to tumor angiogenesis and T cell immunosuppression while IL-8 and IL-6 have been linked to the recruitment of mesenchymal stem cells and neutrophils amongst others." (PMID 30111846, 2018). "We investigated whether the loss of IGF-1R function altered IL-6 expression in the tumor epithelial cell population by measuring IL-6 expression in the CD24+/CD29lo (luminal) and CD24+/CD29hi (basal) cell populations." (PMID 30458886, 2018). "Candidate factors include tumor-secreted molecules previously implicated in MDCS formation, such as GM-CSF, VEGF, IL-1β, IL-6, and prostaglandin E2, but other tumor-derived factors may be involved." (PMID 30235890, 2018). "The use of IL-6 as a diagnostic tumor biomarker demands close attention to the cut-off level." (PMID 30038723, 2018). "Furthermore, the 4T1WT, 4T1NC, and 4T1IL-6low cells were implanted into NOD/SCID mice separately, and the results showed that IL-6 knockdown inhibited tumor growth to some extent in T- and B-cell immunity-deficient mice (P = 0.001)." (PMID 30083161, 2018). "Therefore, IL-6 is closely related to tumor occurrence and development, and understanding the genetic diversity of IL-6 will be helpful for cancer risk prediction and gene therapy." (PMID 29552316, 2018). "Cancer associated fibroblast and tumor cell could secreted interleukin-6 to inhibit and stimulate Alb and Fib, respectively." (PMID 30305803, 2018). "Our work implicates a central role of IL6 in HER2‐mediated CRPC in SPRY2‐deficient tumours." (PMID 29540470, 2018). "Our work suggests that in SPRY2‐deficient tumours IL6 may mediate AR‐dependent CRPC formation by facilitating tumoral androgen biosynthesis, at least in part through enhanced androgen biosynthesis." (PMID 29540470, 2018). "Although the use of IL-6 as an independent diagnostic tumor biomarker seems doubtful, it may be useful as a quick biomarker test in general practice." (PMID 30038723, 2018).
tumor (continued). "Expression of IL-6 and IL-10 (macrophage-associated cytokines) in tumour tissue has only been determined in a few studies and using relatively small patient cohorts with limited information about prognostic significance (e.g. 108 invasive BC cases stained for IL-6 and other cytokines)." (PMID 29256156, 2018). "And there is evidence that in an inflammation-induced tumor model, IL-6 deficiency could relive the promotion of tumor development." (PMID 30382864, 2018). "Regarding the results of this review, some studies find equivocal results when investigating tumor depth invasion or lymph node metastases, but the overall picture seems to indicate that high levels of IL-6 are associated with severe clinical features of patients with GI cancer." (PMID 30038723, 2018). "Finally, both Mo-MDSCs and PMN-MDSCs differentiate into tumor-associated macrophages (TAMs), which facilitate tumor cell growth and survival via secreting IL-6, EGF, and TNF and promote angiogenesis by VEGFA, Semaphorin 4D, and IL-8." (PMID 29541408, 2018). "Both serum IL-6 and serum CA 19.9 were associated with tumor stage." (PMID 30038723, 2018). "Our previous study also demonstrated that tumor-derived IL-6 might play a significant role in the development and accumulation of e-MDSCs in vivo; however, the regulatory mechanisms underlying IL-6-related myeloid differentiation blockage are less understood." (PMID 30083161, 2018). "This was likely due to a developing resistance to therapy since increased serum Shh/IL-6 might reflect an association with resumed tumor growth based on their association with induction of the cancer stem like cells." (PMID 28496132, 2017). "Furthermore, Chop deficiency promotes the anti-tumor activity of tumor-infiltrating myeloid-derived suppressor cells (MDSC) by decreasing IL-6 and phospho-STAT3, delaying tumor progression." (PMID 28860159, 2017). "As IL-6 is highly expressed in BLBC cells as well as infiltrated tumor-associated macrophages (TAMs), it may exert its function of Dub3 activation through autocrine and paracrine loops." (PMID 29088851, 2017). "Interestingly, nuclear PRMT5 expression was directly associated with high IL-6 expression in the primary tumor samples (p < 0.001)." (PMID 28107179, 2017). "In addition, the tumor-associated production of the granulocyte-macrophage colony stimulating factor or thrombopoietin mediated by IL-6 is considered to be responsible for the increase in the PLT observed in cancer patients." (PMID 29285316, 2017). "Interestingly, when an IL-6 antibody was introduced to the murine model, the mice experienced both a significant decrease in tumor-associated neutrophils and a significant improvement in survival compared to the control mice." (PMID 28209123, 2017). "Interleukin-6 (IL-6), a pleiotropic cytokine, is produced by various types of normal and cancer cells and is implicated in the stimulation of tumor cell proliferation, malignant transformation, and tumor progression." (PMID 28878312, 2017). "In addition, phosphorylated STAT3 was constitutively expressed in the SCLC tumors in vivo and a very recent report supports a role for IL-6 produced by tumor-associated macrophages in the paracrine activation of STAT3, in SCLC." (PMID 29020964, 2017). "Under hypoxic conditions, HIF-1alpha leads to anupregulation of PD-L1 expression on MDSCs in the tumor microenvironment, thereby increasing interleukin (IL)-6 and IL-10 secretion from MDSCs, causing a MDSC-induced immunosuppression, T cell inactivation, and promoting tumor progression." (PMID 29250198, 2017). "In this study, we comprehensively evaluated the potential value of serum visfatin in HCC patients, and results indicated that serum visfatin levels were significantly elevated in patients with HCC and were associated with AFP, IL-6, tumor size, and tumor stage." (PMID 28178643, 2017).
tumor (continued). "Indeed, IL-17 induces IL-6 production by tumor cells and/or tumor-associated stromal cells, which results in the activation of STAT3, a well-known oncogenic TF, that up-regulates pro-angiogenic factors." (PMID 28708082, 2017). "Additionally, elevated serum CRP levels are associated with increased IL-6 production by tumor cells or by surrounding tissues." (PMID 29262550, 2017). "Based on this finding, it could be hypothesized that IL-6 sequestration by shCD5 would result in limiting the number and/or function of tumor-associated B10 cells." (PMID 29296231, 2017). "Moreover, we have demonstrated that treadmill training during systemic IL-6 overexpression enhanced mTORC1 signaling and mitochondrial quality control in tumor-bearing mice, which was associated with improved insulin sensitivity." (PMID 29375734, 2017). "In our CID model, tumour burden was associated with increased IL-6, and possibly IL-1β." (PMID 28120908, 2017). "In addition, IL-6 overexpression was also directly associated with tumor recurrence (p < 0.001), perineural invasion (p = 0.007), extracapsular spread (p = 0.014) and inversely associated with p16 status (p = 0.011)." (PMID 28107179, 2017). "Furthermore, Hb levels (Spearman ρ = −0.40, p = 0.0015) and tumor histological grade (p < 0.0001) were associated with IL-6 levels." (PMID 28851899, 2017). "IL-6 may have an important role in cross-talk within the tumour associated bone marrow microenvironment." (PMID 28148268, 2017). "Moreover, a high level of TNF-α in combination with IL-6 in ascites’ fluid and tumor tissue of OC patients is associated with tumor progression and resistance to chemotherapy concomitant with shortened progression-free survival." (PMID 28725636, 2017). "IL-6 is another cytokine expressed in tumor cells, and its dysregulation has been implicated in many diseases including malignant tumors for which it has been associated with tumor progression, drug resistance, and poor prognoses." (PMID 28727766, 2017). "However, IL-6 has also been found to alter the susceptibility of tumor cells to apoptosis by chemotherapeutic drugs." (PMID 28878571, 2017). "Mechanistically, high PIM levels increase the recruitment of tumor/inflammation associated macrophages, MDSCs, mast cells, and neutrophils to the target tissue, by increasing IL-6 locally as well as other cytokines (such as OSM) and probably other chemokines (such as CCL2 and CXCL8)." (PMID 28938604, 2017). "Furthermore, the cytokines IL-6 and IL-1β, previously associated with tumor growth and metastasis, were also up-regulated in both the cell lysate and the supernatant of LuM cells, confirming the results of the expression array analysis." (PMID 28410227, 2017). "The expression of inflammatory-associated cytokines, including IL-1α, IL-1β and IL-6, were significantly reduced in the tumor microenvironment of JC-001-treated mice, suggesting that JC-001 might decrease tumor-induced inflammation." (PMID 28399860, 2017). "Progression in tumor stage and size are associated with high levels of IL-1β, IL-6 and TNF-α." (PMID 27507058, 2016). "In addition, IL-6 overexpression was also directly associated with tumor recurrence (p<0.001), perineural invasion (p=0.005), extracapsular spread (p=0.0107) and inversely associated with HPV status (p=0.0153)." (PMID 26919244, 2016). "Collectively, these data suggest that the expansion of stem-like cancer cells in tumor xenografts from ESE3KD-PrECs was associated with elevation of IL-6 and consequent activation of JAK/STAT3 and that it could be efficiently targeted by JAK/STAT3 inhibitors." (PMID 27732936, 2016). "After 48-h, PDGF-AA secretion remained elevated without evidence of reaching a plateau, suggesting, PDGF-AA is likely the key chemotactic agent underlying MSC chemotaxis in HNSCC and may cause tumor cell release of IL-6 as a later phenomenon." (PMID 27931212, 2016).
tumor (continued). "After activation by IL6, various types of cells, such as tumor-associated macrophages, myeloid-derived suppressor cells, and endothelial cells, are involved in the development of a suppressive immunomicroenvironment and a metastatic tumor microenvironment." (PMID 27163161, 2016). "In a simplified view, tumor infiltrating monocytes, macrophages and Th17 lymphocytes produce cytokines like IL-1, IL-6, IL-17, IL-23 and TNFα, which signal to exacerbate tumor-associated inflammation and activate survival and proliferation machinery in cancer cells." (PMID 31051015, 2016). "miR-26a has been reported to suppress tumor growth and metastasis of HCC through the interleukin (IL)-6-Stat3 signaling pathway, and down-regulation of miR-26a in tumor tissue was associated with poor overall survival for patients who underwent curative surgery for HCC." (PMID 26733151, 2016). "Regarding the downregulation of IL-6 mediated by SOCS3 overexpression, as early as two hours after exposure to 15d-PGJ2, and considering the detrimental effects and actions of IL-6 linked with tumor growth, progression, and relapse, 15d-PGJ2 is presented as a novel antineoplastic drug." (PMID 27190500, 2016). "IL-6 also supports glycolysis, loss of differentiation, tumor growth and angiogenesis." (PMID 26998523, 2016). "Here, we investigated the underlying mechanisms of IL-6 in tumour self-seeding by CTCs." (PMID 26623559, 2016). "Second, tumor cells themselves and tumor-associated leukocytes could produce various inflammatory cytokines, such as tumor necrosis factor-alpha, interleukin-6, and vascular endothelial growth factor." (PMID 27342313, 2016). "We therefore evaluated whether the anti-tumor activity of LFs was associated with its anti-inflammatory properties through inhibiting pro-inflammatory cytokines and mediators (IL-1β, IL-6, TNF-α, iNOS and Cox-2)." (PMID 27563884, 2016). "We then knocked down IL-6 using shRNA to determine whether the loss of IL-6 inhibited CTC attraction to primary tumours." (PMID 26623559, 2016). "High levels of IL-6 are associated with the severity of disease and may promote tumor angiogenesis and cancer, which could be genetically determined at an individual level." (PMID 27220278, 2016). "Moreover, a cytokine panel including both IL-8 and IL-6 showed potential in tumor recurrence risk identification in patients undergoing BCG treatment." (PMID 27660385, 2016). "Similarly, inhibition of MDA-MB-231 tumor xenografts by ulinastatin and docetaxel was associated with downregulation of the expression of IL-6, IL-8 and TNF- α47." (PMID 26888313, 2016). "Interestingly, nuclear myoferlin expression was directly associated with high IL-6 expression in the primary tumor samples (p<0.001)." (PMID 26919244, 2016). "Pro-inflammatory macrophages are generally characterized by the production of high levels of pro-inflammatory mediators, such as TNF-α, IL1-β, IL-6 or IL-12 and are associated with bacterial clearance and tumour cytotoxicity, being considered tumour suppressors." (PMID 27513864, 2016). "The interleukin-6 (IL-6) signaling pathway has also been implicated in tumor progression." (PMID 27007053, 2016). "In this regard, high PIM levels increase the recruitment of tumor/inflammation associated macrophages, MDSCs, mast cells, and neutrophils to the target tissue, which can increase cytokines, such as IL-6, IL-1 and TNFa, and chemokines, such as CCL2 and CXCL8, locally." (PMID 27901106, 2016). "The majority of studies assumed that elevated serum CRP levels in patients with malignancy constituted a bodily response, secondary to tumor necrosis, local tissue damage and inflammation caused by cytokines released from leukocytes infiltrating the tumor microenvironment, in particular IL-6." (PMID 26848624, 2016). "IL-6, produced by tumor-associated macrophage, is an important mediator that promotes tumor growth." (PMID 27006530, 2016).